TRAF2 (TNF receptor associated factor 2)
Diseases named in the same sentence as TRAF2 in open-access papers (continued):
Sharing a sentence is not in itself a finding about the gene and the disease.
renal cell carcinoma (3 papers, 2024 to 2025). "Another study found that TRAF2 favor cancer progression by promoting M2-polarized tumor-associated macrophage infiltration in renal cell carcinoma." (PMID 40612112, 2025). "TRAF2 promotes angiogenesis and cancer progression in renal cell carcinoma by facilitating the infiltration of M2-polarized tumor-associated macrophages." (PMID 41187171, 2025). "Sunitinib, a drug for the treatment of renal cell carcinoma, activates the NF-κB signaling pathway through the IRE1α/TRAF2/IKKβ axis of the ER stress response, enhancing the expression of IL-6, IL-8, and TNF-α." (PMID 38775480, 2024).
schizophrenia (3 papers, 2011 to 2024). A major psychotic disorder characterized by abnormalities in the perception or expression of reality. "Traf2 and Nck-interacting protein kinase (TNIK), a schizophrenia susceptibility gene, is associated with risperidone treatment response." (PMID 39268461, 2024).
Arthritis (2 papers, 2011 to 2021). Inflammation of a joint. "Sphingosine kinase (Sphk1) mediates TNFα-induced arthritis and osteoclastogenesis via TNFα receptor activating factor 2 (TRAF2)." (PMID 34968192, 2021).
brain injury (2 papers, 2019 to 2025). Acute and chronic (see also brain INJURIES, CHRONIC) injuries to the brain, including the cerebral hemispheres, CEREBELLUM, and brain STEM. "PNS can also activate the RIG-I signaling pathway, and inhibit the related signaling molecules, TNF receptor associated factor 2 (TRAF2) and NF-κB, which are essential for the reduction of IS-induced brain injury." (PMID 41322290, 2025).
clear cell renal cell carcinoma (2 papers, 2023 to 2024). "It has been convinced that TRAF2 promote M2-polarized tumor-related macrophage infiltration, cancer progression and angiogenesis and by decreasing autophagy in clear cell renal cell carcinoma." (PMID 38549047, 2024).
Cognitive impairment (2 papers, 2022). Abnormal cognition is characterized by deficits in thinking, reasoning, or remembering. "HMGB1/TLR4/IL-1β/IL-1R pathway, HMGB1/TNF-α/TRADD pathway, and TRAF-2 are the key initiators of neuroinflammation for epilepsy and cognitive impairments." (PMID 35656438, 2022). "ER stress was tightly implicated in cognitive impairment and accumulated unfolded proteins in ER promoted dissociation of ER chaperone GRP78 from IRE, causing IRE interaction with TRAF2 and further activation of downstream target JNK ultimately resulting in apoptosis." (PMID 35260821, 2022).
diabetic retinopathy (2 papers, 2022 to 2024). "Another study reported upregulation of CD40, TRAF2, and TRAF6 in patients with diabetic retinopathy, where CD40 was associated with the expression of pro-inflammatory molecules such as intercellular adhesion molecule 1 (CD54), CCL2, and TNFα." (PMID 38554187, 2024).
epilepsy (2 papers, 2022 to 2024). A brain disorder characterized by episodes of abnormally increased neuronal discharge resulting in transient episodes of sensory or motor neurological dysfunction, or psychic dysfunction. "Traf2-and NcK-interacting kinase (TNIK) has recently attracted attention as a critical modulation target of many neurological and psychiatric disorders, but its role in epilepsy remains unclear." (PMID 38292191, 2024).
idiopathic pulmonary fibrosis (2 papers, 2025). Idiopathic pulmonary fibrosis (IPF) is a nonneoplastic pulmonary disease that is characterized by the formation of scar tissue within the lungs in the absence of any known cause. "The identification of TRAF2 as a critical regulator in pulmonary fibrosis is particularly significant given the increasing prevalence of fibrotic lung diseases, including idiopathic pulmonary fibrosis (IPF) and radiation-induced pulmonary fibrosis." (PMID 40438045, 2025). "While several challenges remain to be addressed, particularly regarding the long-term effects and translation into clinical practice, this research lays the groundwork for future studies targeting TRAF2 in pulmonary fibrosis and other fibrotic diseases." (PMID 40438045, 2025). "To investigate the role of TRAF2 in the progression of pulmonary fibrosis, we first knocked down TRAF2 in A549 cells using three distinct small interfering RNAs (siRNAs)." (PMID 40438045, 2025). "While significant progress has been made in understanding the role of TGF-β and other cytokines in pulmonary fibrosis, the role of TRAF2 in this context remains largely unexplored." (PMID 40438045, 2025). "In conclusion, our study provides novel insights into the role of TRAF2 in pulmonary fibrosis, highlighting its interaction with β-catenin and Snail in regulating key fibrotic pathways." (PMID 40438045, 2025). "We demonstrate that the interaction of TRAF2 with β-catenin and Snail is essential for the progression of pulmonary fibrosis, thereby distinguishing our findings from those that focus solely on either β-catenin or Snail individually." (PMID 40438045, 2025). "TRAF2 orchestrates pulmonary fibrosis through a sophisticated signaling network that converges on multiple pathogenic pathways." (PMID 40438045, 2025). "TRAF2 inhibition emerges as a promising therapeutic strategy, with the potential to alter the course of pulmonary fibrosis and improve patient prognosis." (PMID 40438045, 2025). "Furthermore, we investigate the molecular mechanisms by which TRAF2 regulates pulmonary fibrosis, specifically its interaction with β-catenin and Snail, which promotes β-catenin-mediated transcriptional activation and facilitates EMT." (PMID 40438045, 2025). "Our study provides valuable insights into the role of TRAF2 in pulmonary fibrosis, while the precise molecular mechanisms by which TRAF2 interacts with β-catenin and Snail in fibrosis remain unclear." (PMID 40438045, 2025). "In this study, we identified TRAF2 as a crucial regulator in the progression of pulmonary fibrosis." (PMID 40438045, 2025). "Furthermore, expanding the research to include chronic fibrotic models will provide more comprehensive insights into the potential of targeting TRAF2 as a therapeutic strategy in pulmonary fibrosis." (PMID 40438045, 2025). "Therefore, our study focuses on identifying new molecular targets in the treatment of pulmonary fibrosis, providing an important foundation for future investigations into TRAF2-targeted therapies." (PMID 40438045, 2025). "Moreover, combining TRAF2 inhibition with other existing treatments, such as pirfenidone or nintedanib, may provide synergistic effects in managing pulmonary fibrosis." (PMID 40438045, 2025). "However, the precise molecular mechanism of TRAF2 in pulmonary fibrosis is still unclear." (PMID 40438045, 2025). "In patients with idiopathic pulmonary fibrosis (IPF), TRAF2 overexpression is correlated with elevated TNF-α levels." (PMID 40438045, 2025). "More recent evidence suggested that TRAF2 stimulates fibroblast activation and ECM deposition by modulating pro-inflammatory and pro-fibrotic signaling pathways in pulmonary fibrosis." (PMID 40438045, 2025). "In this study, we investigate the role of TRAF2 in modulating β-catenin and Snail, ultimately influencing fibroblast activation and EMT in pulmonary fibrosis." (PMID 40438045, 2025).
idiopathic pulmonary fibrosis (continued). "For instance, investigating how TRAF2 affects fibroblast-to-myofibroblast differentiation and ECM remodeling would provide deeper insights into its role in pulmonary fibrosis." (PMID 40438045, 2025). "To evaluate the impact of inhibiting TRAF2 signaling in vivo, we utilized the TNIK inhibitor (KY05009) in mice with pulmonary fibrosis induced by irradiation." (PMID 40438045, 2025). "Within 30 months, Insilico Medicine’s ISM001-055, an AI-engineered inhibitor aimed against Traf2- and Nck-interacting kinase (TNIK) for idiopathic pulmonary fibrosis, progressed from concept to phase I trials, demonstrating the efficacy of AI in pharmaceutical development." (PMID 40547482, 2025).
Lyme disease (2 papers, 2022 to 2023). Lyme disease (named after the towns in the USA where the disease was first identified) is a bacterial infection caused by Borrelia burgdorferi. "We next asked whether the activity of IRE1α-TRAF2 signaling was restrictive to different tick-borne microbes, such as the Lyme disease-causing spirochete B. burgdorferi." (PMID 35862781, 2022).
lymph node metastasis (2 papers, 2019 to 2025). "Cox regression analysis reveals that TRAF2 hypomethylation, lymph node metastasis, distant metastasis, as well as differentiation are vital prognostic factors in GC." (PMID 31130821, 2019). "Regarding lymph node metastasis, in pathologic N, KHDC4 exhibited a positive correlation with TRAF2 (Spearman’s correlation = 0.3481, p < 0.0001)." (PMID 40560737, 2025).
ovarian tumor (2 papers, 2013 to 2022). "This included genes in the NFkB pathway (e.g., NKFBIA, NKFBIE, TRAF2, RELA), which were downregulated among ovarian tumors from patients with greater lifetime ovulatory years." (PMID 35562768, 2022).
psoriasis (2 papers, 2015 to 2025). An autoimmune condition characterized by red, well-delineated plaques with silvery scales that are usually on the extensor surfaces and scalp. "Our results highlight the important role TRAF2 plays to protect keratinocytes from cell death and to down-regulate inflammatory responses and support the idea that intrinsic defects in keratinocytes can initiate psoriasis-like skin inflammation." (PMID 26701909, 2015). "Absence of TRAF2 in keratinocytes in vivo resulted in psoriasis-like epidermal hyperplasia and skin inflammation." (PMID 26701909, 2015).
Sepsis (2 papers, 2022 to 2024). Sepsis is defined as life-threatening organ dysfunction caused by a dysregulated host response to infection. "A time course study using splenic CD11c+ DCs isolated from CLP mice revealed that the phosphorylation of p65 and IκBα was highest at 24 h after sepsis, in parallel with the activation of TNF receptor-associated factor 2 (TRAF2), which served as a pivotal adaptor in transmitting signals from TNFRSF." (PMID 35832091, 2022).
thyroid cancer (2 papers, 2023 to 2024). "However, a diminished expression of TRAF2 was observed in thyroid carcinoma (THCA)." (PMID 38825674, 2024).
allergic asthma (1 paper, 2015). A asthma with a basis in a pathological type I hypersensitivity reaction. "Therefore, kaempferol was effective in ameliorating mucus hypersecretion through disturbing TGF-β-triggered ER stress signaling of IRE1α-TRAF2-JNK in cellular or animal models of allergic asthma." (PMID 26599511, 2015).
Alzheimer disease (1 paper, 2014). A progressive, neurodegenerative disease characterized by loss of function and death of nerve cells in several areas of the brain leading to loss of cognitive function such as memory and language. "Verification of temporal logic formulas in Alzheimer's disease indicates that, overexpressed/mutated TRAF2, NFκB or ASK1 in the cell will promote the synthesis of Amyloid-β (Aβ), leading to the pathogenesis of AD in the future." (PMID 25522186, 2014). "Using the model checking method, we verified several Alzheimer's disease and cancer-related properties, and also identified important proteins (NFκB, ATF4, ASK1 and TRAF2) in the ER-Golgi network, which might be responsible for the pathogenesis of cancer and AD." (PMID 25522186, 2014).
asthma (1 paper, 2020). "In addition, high level of TRAF2 expression in asthmatic rats and humans showed that it is more likely involved in the inflammatory mechanism of asthma possibly through airway epithelial cells and inflammatory cells." (PMID 33072165, 2020).
bladder urothelial carcinoma (1 paper, 2019). "In bladder urothelial carcinoma (BC), receptor-interacting protein kinase 4 (RIPK4) promotes TRAF2 and subsequent NF-κB signaling pathway, ultimately, promotes BC cell aggressiveness." (PMID 31130821, 2019).
blood disease (1 paper, 2016). A disease that occurs in the blood. "Consequently, hindering NF-κB by controlling upstream regulatory molecules such as RIP1 and TRAF2 might be a more efficient and less cytotoxic approach in comparison to Bortezomib for the treatment of blood diseases." (PMID 27098354, 2016).
cardiac ischemia (1 paper, 2019). "However, TRAF2 is reported to play a protective role in cardiac ischemia, as TRAF2 expression in the heart is induced following pressure overload and attenuates myocardial infarction." (PMID 30988281, 2019).
cyst (1 paper, 2011). A sac-like closed membranous structure that may be empty or contain fluid or amorphous material. "We identified changes in gene expression related to cyst growth such as components of MAPK (e.g. Map3k12, Fgf10, Prkcb, Traf2) and TGF-β (e.g. Pitx2) signaling that were up-regulated in the Pkd1-/- animals." (PMID 21518438, 2011).
cystadenoma (1 paper, 2025). A benign or borderline cystic epithelial neoplasm arising from the glandular epithelium. "Regarding TRAF2, RIPK1, TNFRSF10D/TRAIL-R4, and NF-ΚB, differential mRNA expression profiles were identified between the cystadenoma and EOC groups, with statistically significant differences observed between primary and metastatic EOC." (PMID 40943317, 2025).
dermatitis (1 paper, 2025). An inflammatory process affecting the skin. "Related to dermatitis, we found an upregulation of CD74, BTLA, TRAF2, TNIP1, and IL19." (PMID 41416938, 2025).
experimental autoimmune encephalomyelitis (1 paper, 2019). An autoimmune demyelinating disease of the central nervous system that is produced experimentally in animals by the injection of homogenized brain or spinal cord in Freund's adjuvant. "Here we investigated the role of the CD40 downstream signaling intermediates TNF receptor‐associated factor 2 (TRAF2) and TRAF6 in MHCII+ cells in experimental autoimmune encephalomyelitis (EAE)." (PMID 30471110, 2019).
head and neck carcinoma (1 paper, 2011). A carcinoma that arises from the head and neck region. "Given this cellular behavior of the head and neck carcinoma in which this particular signaling pathway is already activated, it is plausible that NSP 5a3a may be altering this signaling pathway in favor of apoptosis through use of TRAF2 and TRADD." (PMID 22170762, 2011).
hepatitis B (1 paper, 2023). "TRAF2 was favorably linked with circulating indicators of liver injury and the degree of hepatic fibrosis in patients with hepatitis B. Our findings also showed that immunological T cells were the major cell type expressing TRAF2." (PMID 37091870, 2023). "TRAF2 expression was abnormally high in hepatic fibrosis in patients with hepatitis B compared with healthy controls." (PMID 37091870, 2023). "In order to further validate enhanced TRAF2 expression in hepatic fibrosis, 10 normal liver tissues and 10 liver tissues with hepatic fibrosis in hepatitis B were acquired." (PMID 37091870, 2023). "Our study screened 1,105 DEGs at the genomic level for further bioinformatic analysis, and we identified TRAF2 as a potential target for hepatic fibrosis treatment in hepatitis B." (PMID 37091870, 2023). "This suggests that TRAF2 is important for T-lymphocyte-dominated immune regulation in hepatic fibrosis in hepatitis B and may influence hepatic fibrosis development through it." (PMID 37091870, 2023). "Therefore, utilizing liver samples from individuals with hepatitis B-induced liver fibrosis, we examined the protein and mRNA levels of TRAF2." (PMID 37091870, 2023). "More intriguingly, TRAF2 showed a significant correlation with the severity of hepatic fibrosis in hepatitis B, suggesting that TRAF2 may also play an important role in human hepatic fibrosis in hepatitis B." (PMID 37091870, 2023).
Hyperglycemia (1 paper, 2023). An increased concentration of glucose in the blood. "These in-vitro findings strongly support the idea that maternal hyperglycemia inhibits fetal lung vasculogenesis in vivo by upregulating TRAF2-mediated GβL-ubiquitination and consequently promoting mTORC1 formation over mTORC2 formation." (PMID 36927703, 2023).
infarction (1 paper, 2019). A localised pathological necrosis of tissue resulting from obstruction of the blood supply usually by a thrombus, an embolus, or vascular torsion. "Striatal knockdown of TRAF2 increased infarction size, cell death, microglial activation and the expression of pro-inflammatory markers at 24 h after reperfusion." (PMID 30988281, 2019).
influenza infection (1 paper, 2013). "Indeed, the TRAF2 dependent TNFRs 4-1BB and GITR have been shown to prolong CD8 T cell survival in the lung during influenza infection, thus TNFR2-dependent loss of TRAF2 may contribute to a decrease in survival signaling through these receptors." (PMID 23874808, 2013).
liver fibrosis (1 paper, 2023). "Additionally, immunofluorescence co-localization was used to identify TRAF2 expression in different cells in liver tissues with HBV-associated liver fibrosis." (PMID 37091870, 2023). "However, more studies are needed to confirm that TRAF2 may accelerate the progression of HBV-associated liver fibrosis by encouraging the release of the inflammatory factors TNFα and IL8 through the TAK1/P38 or TAK1/NF-kB signaling pathways." (PMID 37091870, 2023). "TRAF2 protein expression was significantly higher in the hepatic fibrosis group than in the control group, according to Western blotting (WB)." (PMID 37091870, 2023). "The degree of hepatic fibrosis and serum levels of glutamate transaminase (ALT), aspartate aminotransferase (AST), and total bilirubin (TBIL) were positively linked with TRAF2 expression." (PMID 37091870, 2023). "Based on the immunohistochemical data of TRAF2, TRAF2 expression was substantially correlated with the severity of liver fibrosis and increased with it (p = 0.0001, R = 0.9745)." (PMID 37091870, 2023). "This shows that TRAF2 also may accelerate the development of HBV-related liver fibrosis by releasing the inflammatory factors TNFα and IL8 through the TAK1/P38 or TAK1/NF-kB signaling pathways." (PMID 37091870, 2023). "TRAF2 expression in hepatic fibrosis groups was significantly higher than in the control group." (PMID 37091870, 2023). "TRAF2 may be crucial in controlling T lymphocyte-mediated liver fibrosis." (PMID 37091870, 2023). "Further evidence supports that TRAF2 is involved in collagen I transport via tyrosine kinase-interacting kinase (TNIK), and thus in the progression of liver fibrosis in mice." (PMID 37091870, 2023). "However, TRAF2 has not been studied in liver fibrosis caused by HBV." (PMID 37091870, 2023).
lung squamous cell carcinoma (1 paper, 2025). "The Clinical Proteomic Tumor Analysis Consortium (CPTAC) suggests that the expression of TRAF2 is significantly positive correlated with CD47 protein levels in lung squamous cell carcinoma (LUSC) among 12 types of tumor." (PMID 39665172, 2025).
medulloblastoma (1 paper, 2024). A malignant, invasive embryonal neoplasm arising from the cerebellum. "We identified a rare heterozygous germline loss-of-function variant in the tumor necrosis factor receptor-associated factor 2 (TRAF2) in a young adult patient diagnosed with medulloblastoma." (PMID 39707575, 2024). "We further performed comparative analysis with an in-house cohort of 20 medulloblastomas sequenced using the same platform, revealing an atypical molecular profile of the TRAF2-associated medulloblastoma." (PMID 39707575, 2024). "Integrative genomics revealed a biallelic loss of TRAF2 via partial copy-neutral loss-of-heterozygosity of 9q in the medulloblastoma genome." (PMID 39707575, 2024).
Myocardial fibrosis (1 paper, 2018). "Mouse expressing TRAF2 also showed a 4.4-fold increase in collagen content in the extracellular matrix, thus depicting the induction of myocardial fibrosis." (PMID 30186311, 2018).